PTPRO (protein tyrosine phosphatase receptor type O)
Description:
Possesses tyrosine phosphatase activity. Plays a role in regulating the glomerular pressure/filtration rate relationship through an effect on podocyte structure and function (By similarity).
Synonyms: R-PTP-O; PTP-U2; GLEPP1; PTPU2; PTP-oc; NPHS6; PTPROT
Tractability: Small molecule: it has a high-quality binding pocket. Antibody: UniProt predicts a signal peptide or a membrane-spanning region; its Gene Ontology location is reachable by antibodies, with medium confidence. PROTAC: ubiquitination databases record sites on it; its protein half-life has been measured; a small molecule that binds it is known.
Target class: Enzyme; Hydrolase
Gene: Protein-coding gene on chromosome 12 (15,322,257 to 15,602,175, forward strand). Ensembl gene ENSG00000151490.
Subcellular location: Membrane
Pathways (Reactome):
Signal Transduction: Signaling by NTRK3 (TRKC)
Gene Ontology:
Molecular function: cadherin binding; protein binding; protein tyrosine phosphatase activity; phosphatase activity; protein homodimerization activity; transmembrane receptor protein tyrosine phosphatase activity; Wnt-protein binding; identical protein binding
Biological process: glomerulus development; monocyte chemotaxis; axon guidance; cell morphogenesis; lamellipodium assembly; negative regulation of canonical Wnt signaling pathway; negative regulation of cell-substrate adhesion; negative regulation of glomerular filtration; negative regulation of neuron projection development; negative regulation of retinal ganglion cell axon guidance; podocyte differentiation; regulation of glomerular filtration; slit diaphragm assembly; regulation of synapse organization
Cellular component: extracellular exosome; apical plasma membrane; axon; dendritic spine; GABA-ergic synapse; glutamatergic synapse; growth cone; lamellipodium; lateral plasma membrane; membrane; neuron projection; plasma membrane; postsynaptic density membrane
Genetic constraint (gnomAD): Loss-of-function variants: 58 observed, 140.77 expected, observed/expected ratio (o/e) 0.41, 90% interval 0.33 to 0.51. The upper end of that interval is the gene's LOEUF score, 0.51, which puts it in group 2 of 6, group 1 being the genes least tolerant of losing a copy. Missense variants: 1,324 observed, 1,526.4 expected, observed/expected ratio (o/e) 0.87, 90% interval 0.83 to 0.91. Synonymous variants: 557 observed, 529.87 expected, observed/expected ratio (o/e) 1.05, 90% interval 0.98 to 1.13.
Homologues: Orthologues: chimpanzee PTPRO (99% identical), macaque PTPRO (99% identical), dog PTPRO (97% identical), rabbit PTPRO (97% identical), pig PTPRO (95% identical), guinea pig PTPRO (95% identical), mouse Ptpro (92% identical), rat Ptpro (91% identical), tropical clawed frog ptpro (69% identical), zebrafish ptpro (33% identical), Drosophila melanogaster Ptp10D (28% identical), Drosophila melanogaster Ptp4E (27% identical), and 1 more. Paralogues in human: PTPRB (22% identical), PTPRJ (20% identical), PTPRH (19% identical), PTPRF (18% identical), PTPRD (17% identical), PTPRS (17% identical), PTPRM (16% identical), PTPRK (16% identical), PTPRU (16% identical), PTPRT (16% identical), PTPN13 (15% identical), PTPRZ1 (15% identical), and 23 more.
Diseases named in the same sentence as PTPRO in open-access papers:
PTPRO is named in the same sentence as 88 diseases in open-access papers, as found by Europe PMC text mining. Sharing a sentence is not in itself a finding about the gene and the disease. The quoted sentences say what the papers report.
breast carcinoma (19 papers, 2013 to 2025). "Together, these data strongly demonstrate that the prognostic signature derived from PTPRO-associated immunomodulators was an independent predictor of OS in breast cancer patients." (PMID 36003382, 2022). "We have reported previously that PTPRO promoter hypermethylation is associated with poor survival for patients with ERBB2-positive breast cancer." (PMID 35431974, 2022). "Co-cultured with PTPRO-overexpressing breast cancer cells increased the proportion of M1-like tumor-associated macrophages (TAMs) while decreased that of M2-like TAMs." (PMID 34650968, 2021). "By evaluating the association between PTPRO and macrophage infiltration, we found that PTPRO increased M1-like TAMs, while decreased M2-like TAMs in breast cancer." (PMID 34650968, 2021). "PTPRO (protein tyrosine phosphatase receptor type O) has been described as highly expressed in the microenvironment of breast cancer, associated with increased tumor growth, angiogenesis, and metastatic spreading." (PMID 33381116, 2020). "We screened primary breast cancer tissues for PTPRO promoter hypermethylation and assessed potential associations with pathological features and patient outcome." (PMID 24919593, 2014). "We also demonstrated the essentiality of its catalytic activity in suppressing breast cancer lung metastasis, as evidenced by the observation that PTPRO with an active site mutation failed not only to dephosphorylate JAK2 and YAP but also to inhibit breast cancer lung metastasis." (PMID 40016288, 2025). "We first used ESTIMATE and ssGSEA to determine whether PTPRO expression is associated with the levels of CD8+ T-cell infiltration in breast cancer immune infiltrates." (PMID 36003382, 2022). "Bioinformatical analyses revealed that PTPRO was closely associated with immune infiltration, and positively correlated to M1-like macrophages, but negatively correlated to M2-like macrophages in breast cancer tissues." (PMID 34650968, 2021). "Loss of PTPRO in the tumor niche is correlated with tumor metastases of breast cancer." (PMID 34650968, 2021). "We examined the methylation status of PTPRO in primary breast tumors and matched peripheral blood samples and determined if promoter methylation was associated with decreased gene expression in breast cancer cell lines." (PMID 24919593, 2014). "To do this, we determined the methylation status of the PTPRO gene promoter in 221 Chinese women with sporadic breast cancer and investigated whether PTPRO methylation was associated with clinicopathologic parameters and clinical outcome." (PMID 24090193, 2013). "However, the role and underlying mechanisms of PTPRO in breast cancer lung metastasis are largely unknown." (PMID 40016288, 2025). "In summary, we have demonstrated through both in vivo and in vitro experiments that PTPRO suppresses breast cancer metastasis." (PMID 40016288, 2025). "Data from patient, animal and cell-based models collectively demonstrated that PTPRO suppresses breast cancer lung metastasis by inhibiting JAK2–YAP dephosphorylation." (PMID 40016288, 2025). "Consistent with this, in previous research, we demonstrated that PTPRO impedes the occurrence and progression of Her2-positive breast cancer by dephosphorylating ERBB26." (PMID 40016288, 2025). "Mechanistically, PTPRO suppresses breast cancer lung metastasis by dephosphorylating JAK2 and inhibiting the JAK2–YAP pathway." (PMID 40016288, 2025). "In this study, we demonstrated that the loss of PTPRO correlated with epithelial‒mesenchymal transition (EMT) and breast cancer lung metastasis." (PMID 40016288, 2025). "Here, we demonstrated that PTPRO suppresses breast cancer lung metastasis by targeting the JAK2–YAP axis." (PMID 40016288, 2025).
breast carcinoma (continued). "IHC staining also showed that the levels of PTPRO were positively and negatively correlated with those of E-cad and N-cad, respectively, in both animal model and human breast cancer samples." (PMID 40016288, 2025). "Analysis of catalytic-dead PTPRO mutant breast cancer cells confirmed that functional PTPRO is a determinant of the activation of the JAK2–YAP pathway and the suppression of breast cancer metastasis." (PMID 40016288, 2025). "Conversely, our investigation revealed that PTPRO has an inhibitory effect on breast cancer lung metastasis." (PMID 40016288, 2025). "Bioinformatics analyses and subsequent assays of human breast cancer specimens revealed a reverse correlation between PTPRO expression and JAK2–YAP pathway activity." (PMID 40016288, 2025). "We have also shown that PTPRO can suppress breast cancer progression by affecting the phosphorylation status of ERBB2 and related downstream pathways." (PMID 40016288, 2025). "Several pieces of research have suggested the potential growth-suppressor and anti-tumorigenesis properties of PTPRO, notably in hepatocellular carcinoma, breast cancer and colorectal tumor." (PMID 38182570, 2024). "We then conducted IHC analysis of PTPRO on a tissue microarray (TMA) containing 180 human breast cancer samples and 18 normal breast tissues." (PMID 35431974, 2022). "PTPRO significantly impacts CD8+ T-cell infiltration in breast cancer, suggesting a potential role of immunomodulation." (PMID 36003382, 2022). "Next, we analyzed two public available datasets GSE38376 and GSE16179 and found that the PTPRO mRNA level is lower in lapatinib-resistant breast cancer cells (SKBR3-lapR and BT474-lapR) than that of their parental cells (SKBR3-P and BT474-P)." (PMID 35431974, 2022). "We next assessed the impact of PTPRO on the lapatinib resistance in ERBB2-positive breast cancer cells." (PMID 35431974, 2022). "On the contrary, protein tyrosine phosphatase receptor type O (PTPRO) in EVs produced by breast cancer cells induces M1 polarization via inactivating the STAT signaling pathway and then inhibits tumor migration." (PMID 36405712, 2022). "Relationship between PTPRO expression and clinicopathologic variables in tissue samples of breast cancer patients (n = 180)." (PMID 35431974, 2022). "We found in this study that the expression level of PTPRO in breast cancer tissues is lower than that of the normal tissue." (PMID 35431974, 2022). "In our previous study, we explore the potentials of reexpressing PTPRO by using 5-azacytidine in ERBB2-positive breast cancer cells." (PMID 35431974, 2022). "Overall, through these methods above, we can overexpress PTPRO in breast cancer and overcome the resistance in patients." (PMID 35431974, 2022). "Altogether, our data strongly suggest that upregulated PTPRO in ERBB2-positive breast cancer cells can enhance lapatinib sensitivity." (PMID 35431974, 2022). "In the present study, we found that tumor-derived exosomal PTPRO triggered M1-like macrophage polarization to suppress the migration and invasion of breast cancer cells." (PMID 34650968, 2021). "To determine the effects of PTPRO expressed in cancer cells on macrophage polarization, we first generated stable PTPRO-overexpressing and PTPRO-knock down breast cancer cells, ZR-75-1-PTPRO and ZR-75-1-shPTPRO, respectively." (PMID 34650968, 2021). "To investigate the impact of PTPRO on TME, we systematically analyzed the correlation of PTPRO and immune infiltration using multiple public breast cancer datasets." (PMID 34650968, 2021). "Further in vitro experiments indicated that inhibition of PTPRO suppresses the proliferative abilities of tumor cells in pancreatic cancer, blood cancer, and breast cancer." (PMID 35003364, 2021). "Previously, we reported that the DNA methylation status of PTPRO is a prognostic factor in ERBB2-positive breast cancer." (PMID 34650968, 2021).
breast carcinoma (continued). "Taken together, the data demonstrated that breast cancer cell-derived exosomal PTPRO induced macrophages to differentiate toward M1-like phenotype." (PMID 34650968, 2021). "Our data suggested that exosomal PTPRO inhibited breast cancer invasion and migration by modulating macrophage polarization." (PMID 34650968, 2021). "Our study highlights the critical role of exosomal PTPRO in suppressing breast cancer invasion and migration." (PMID 34650968, 2021). "Evidence indicates that PTPRO can be downregulated via methylation in some forms of tumors, such as breast cancer, hepatocellular carcinoma, lung cancer, chronic lymphocytic leukemia, and esophageal carcinoma 13-18." (PMID 35003364, 2021). "We focus on TAMs throughout the current study based on the correlation of PTPRO expression and macrophage infiltration that we found in patients with breast cancer." (PMID 34650968, 2021). "Here, we demonstrated that tumor derived PTPRO-expressing exosomes induced macrophages to differentiate to M1 phenotype, and inhibited breast cancer cell invasion and migration." (PMID 34650968, 2021). "In summary, our studies showed that tumor cell-derived exosomal PTPRO inhibits invasion and migration abilities of breast cancer cells via modulating TAM polarization." (PMID 34650968, 2021). "This was particularly evident for ER+, PR+, and HER2-amplified breast cancer subgroups, which all showed that PTPRO methylation in tumor tissues was a strong prognostic factor." (PMID 24919593, 2014). "The data we present here, in conjunction with earlier work, establish PTPRO as a likely tumor suppressor in breast cancer." (PMID 24919593, 2014). "Another study found that low expression of PTPRO correlated with reduced survival for HER2-positive breast cancer patients." (PMID 24919593, 2014). "The current study is the first to report an association between PTPRO methylation and positive lymph node status and HER2 amplification in breast cancer." (PMID 24919593, 2014). "PTPRO methylation has been further confirmed to be clinically relevant in breast cancer, particularly in HER2-amplified patients." (PMID 24919593, 2014). "Among matched peripheral blood samples from breast cancer patients, 33 of 98 (34%) exhibited methylated PTPRO in plasma." (PMID 24919593, 2014). "PTPRO methylation was detected in two of three breast cancer cell lines and in 53 of 98 (54%) primary human breast cancer specimens; however, no PTPRO methylation was observed in adjacent normal tissue." (PMID 24919593, 2014). "Methylation of the PTPRO promoter has been demonstrated in different tumor types, including breast cancer." (PMID 24919593, 2014). "Previous studies have reported methylation-mediated down-regulation of PTPRO expression in breast cancer and other tumor types, such as rat hepatocellular carcinoma, human chronic lymphocytic leukemia, human lung cancer, esophageal carcinoma." (PMID 24919593, 2014). "In the current study we investigated the methylation status of PTPRO in primary human breast cancer from fresh frozen specimens with the aim of defining the frequency of this epigenetic aberration in the disease." (PMID 24919593, 2014). "We next sought to determine the relationship between PTPRO methylation and gene expression in a panel of breast cancer cell lines (MCF-7, MDA-MB-231, and Hs578t) and in normal human mammary epithelial cells (HMEC, 48R)." (PMID 24919593, 2014). "PTPRO methylation is a common event in the primary breast cancer and can be reliably detected in peripheral blood samples." (PMID 24090193, 2013). "A previous study examined 21 breast cancer specimens and found 17 cases (81%) that had dense hypermethylation in the CpG island of the PTPRO gene, whereas the adjacent normal tissue remained unmethylated." (PMID 24090193, 2013).
breast carcinoma (continued). "In order to access its clinical application potential as a biomarker in peripheral blood, we further examined PTPRO in 24 matched plasma samples from breast cancer patients and 10 plasma samples from a normal control cohort." (PMID 24090193, 2013). "PTPRO methylation is a common event in primary breast cancer and can be reliably detected in peripheral blood samples." (PMID 24090193, 2013). "We extend these studies, using a much larger sample size, to show a similar 74.3% (130/175) incidence of PTPRO methylation in breast cancer." (PMID 24090193, 2013). "A chi-square test suggested hypermethylation of PTPRO promoter occurs specifically and frequently in primary breast cancer (P < 0.000)." (PMID 24090193, 2013). "We further explored the feasibility of detecting PTPRO methylation in the plasma of matched peripheral blood samples from breast cancer patients." (PMID 24090193, 2013). "Our larger sample size enables us to conclude that the PTPRO methylation is a common event in primary breast cancer." (PMID 24090193, 2013). "PTPRO methylation is associated with poor survival only in HER2-positive patients, suggesting use of PTPRO methylation as a prognostic factor for breast cancer and for optimizing individualized therapy for HER2-positive patients." (PMID 24090193, 2013). "Given the critical function of PTPRO in inhibiting metastasis, targeting PTPRO could be a potential therapeutic strategy for preventing breast cancer lung metastasis." (PMID 40016288, 2025). "To determine whether PTPRO plays a role in BC cell lung metastasis, we established a mouse mammary tumour model (Ptpro+/+PyMT and Ptpro−/−PyMT), and the nodules in the lungs were examined when the size of the tumour reached approximately 1200 mm3." (PMID 40016288, 2025). "Protein tyrosine phosphatase receptor type O significantly affects CD8+ T cell infiltration in breast cancer and it could be used to predict immunotherapy efficacy and prognosis in breast cancer." (PMID 38783893, 2024). "Furthermore, depletion of PTPRO from ERBB2-positive breast cancer cells SKBR3 and BT474 also reduced their lapatinib sensitivity." (PMID 35431974, 2022). "Besides, we have previously demonstrated that PTPRO inhibited ERBB2-driven breast cancer through dephosphorylation leading to dual effects of ERBB2 signaling suppression and endosomal internalization of ERBB2." (PMID 34650968, 2021). "We next used transwell assays to determine whether the switching of macrophage phenotype driven by PTPRO-exo is responsible for preventing migration and invasion of breast cancer cells." (PMID 34650968, 2021). "Moreover, tumor cell-derived exosomal PTPRO inhibited breast cancer cell invasion and migration, and inactivated STAT signaling in macrophages." (PMID 34650968, 2021). "In this study, we showed that PTPRO plays a role in immune infiltration in breast cancer." (PMID 34650968, 2021). "Here, we report that tumor PTPRO methylation is a strong prognostic factor in breast cancer." (PMID 24919593, 2014). "Tumor-specific PTPRO promoter methylation was documented in primary human breast cancer cases." (PMID 24919593, 2014). "Taken together, these data support a role for PTPRO as a tumor suppressor in breast cancer and suggest that its methylation and expression may have prognostic significance in the disease." (PMID 24919593, 2014). "More recently, a tumor suppressive role for PTPRO in breast cancer has emerged." (PMID 24919593, 2014). "In addition, demethylation induced by 5-azacytidine led to gene reactivation in PTPRO-methylated and -silenced breast cancer cell lines." (PMID 24919593, 2014).